ATXN2 (ataxin 2)
Diseases named in the same sentence as ATXN2 in open-access papers (continued):
Sharing a sentence is not in itself a finding about the gene and the disease.
spinocerebellar ataxia type 1 (8 papers, 2012 to 2025). Spinocerebellar ataxia type 1 (SCA1) is a subtype of type I autosomal dominant cerebellar ataxia (ADCA type I) characterized by dysarthria, writing difficulties, limb ataxia, and commonly nystagmus and saccadic abnormalities. "Spinocerebellar ataxia type 1 (SCA1, MIM 164,400) and type 2 (SCA2, OMIM 183090) are autosomal dominant inherited diseases caused by an expansion of a highly polymorphic CAG repeat sequence within the coding region of the ATXN1 and ATXN2 gene, respectively." (PMID 38954239, 2024). "Moreover, we observed that FOX-2 directly interacts with ataxin-2, a protein modulating spinocerebellar ataxia type 1 pathogenesis." (PMID 22666429, 2012).
proteinopathy (7 papers, 2019 to 2024). "Thus, ATXN2 is a unique protein in that its different polyQ expansions are associated with two different proteinopathies, polyQ disease and TDP-43 proteinopathies." (PMID 33115537, 2020). "Further implicating Ataxin-2 in ALS, antisense oligonucleotides (ASOs) or RNAi targeting ATXN-2 mRNA provide marked protection against motor deficits in mouse models of TDP-43 proteinopathy and SCA2." (PMID 39739690, 2024). "Although the contribution of ATXN2 to TDP-43 proteinopathies has been studied mostly in ALS, recent studies reported the pathogenic role of ATXN2 in FTLD as a phenotypic modifier." (PMID 33115537, 2020). "Down-regulation of Ataxin-2 has been shown to mitigate TDP-43 proteinopathy in ALS models." (PMID 39739690, 2024). "While the pathological involvement of mutant ATXN2 with a highly expanded polyQ tract in SCA2 has been intensively investigated, the association between ATXN2 with a normal or intermediately expanded polyQ tract and the pathogenesis of TDP-43 proteinopathies is largely unknown." (PMID 33115537, 2020). "Further investigations employing brains from a larger number of cases are needed to confirm our observations and to clarify the pathological role of ATXN2 in FTLD-TDP and other TDP-43 proteinopathies." (PMID 33115537, 2020). "Taken together, we concluded that overexpression of HDAC6 attenuates UPS impairment in TDP-43/ATXN2 flies, which is similar to what was found in the cell-based TDP-43 proteinopathy model." (PMID 33282865, 2020). "It remains to be clarified whether reduced ATXN2 expression induces neurodegeneration by impairing protein synthesis or plays a neuroprotective role by attenuating the toxicity of TDP-43 aggregates in FTLD-TDP and other TDP-43 proteinopathies." (PMID 33115537, 2020).
Alzheimer disease (6 papers, 2015 to 2025). A progressive, neurodegenerative disease characterized by loss of function and death of nerve cells in several areas of the brain leading to loss of cognitive function such as memory and language. "Genomic and transcriptomic approaches reveal disease-specific risk genes (e.g., TREM2 in Alzheimer’s disease, ATXN2 in ALS) and biomarkers, enabling more precise diagnosis and personalized medicine." (PMID 40805906, 2025). "Several recent studies have implicated a range of genes, including Sv2b, Park2, Sept5, and Atxn2, in the development of neurological disorders, cognitive impairment, and neurodegenerative diseases such as Alzheimer’s disease (AD) and Parkinson’s disease (PD)." (PMID 40943361, 2025). "Impressive recent work has shown that reducing levels of TIA1 or ataxin-2 delays disease progression in models for Alzheimer's disease (AD) or ALS, respectively, further supporting the importance of RBPs in neurodegenerative diseases." (PMID 31138677, 2019).
autoimmune disease (6 papers, 2014 to 2023). A disorder resulting from loss of function or tissue destruction of an organ or multiple organs, arising from humoral or cellular immune responses of the individual to their own tissue constituents. "ATXN2 has been reported to be associated with several autoimmune diseases like T1D, CD, and CeD by GWAS." (PMID 33541344, 2021). "Associations with parents' attained age were also present for rs7137828 (48.3% frequency, p=3.4×10−14) near ATXN2, coding for Ataxin-2 which is involved in endocytosis and is associated with blood traits and autoimmune disease." (PMID 29227965, 2017). "rs11065979 (chromosome 11) is located near the ATXN2 gene, which is known to be associated with autoimmune disease and blood traits." (PMID 29227965, 2017). "In contrast, the pattern of shared regional genetic associations of SUA level with multiple disease outcomes at ATXN2/S2HB3 locus was more consistent with a pleiotropic model, where we interpreted this locus influenced a cluster of cardiovascular diseases and autoimmune disorders." (PMID 29437585, 2018). "The strongest pleiotropic locus was the ATXN2/SH2B3, where three SNPs (rs653178, rs4766578 and rs3184504) in near-complete LD (r2=0.99) were tagged as the lead SNPs associated with 10 disease groups/outcomes as a cluster of cardiovascular diseases and autoimmune disorders." (PMID 29437585, 2018). "Our analysis highlighted a locus (ATXN2/S2HB3) that may influence SUA level and multiple cardiovascular and autoimmune diseases via pleiotropy." (PMID 29437585, 2018).
neuroblastoma (6 papers, 2015 to 2024). Neuroblastoma (NB) is the most common solid, extracranial childhood tumor. "ATXN2 plays a crucial role in regulating the susceptibility of neuroblastoma cells to apoptotic stimuli both in vitro and in vivo." (PMID 39039334, 2024). "In human neuroblastoma cells, ATXN2 transcriptional suppression via mTOR increases significantly following food restriction." (PMID 39039334, 2024). "In HEK293T cells, ALS patient-derived lymphoblast cell lines and differentiated neuroblastoma cells (M17 cells), intermediate polyQ expansion of ATXN2 (31-32Q) induced caspase-3 activation under stress." (PMID 28587229, 2017). "In contrast, in SH-SY5Y neuroblastoma cells under stress, knockdown of either ATXN2 or PINK1 enhanced the expression of the other." (PMID 28587229, 2017). "In neuroblastoma, ATXN2 overexpression sensitizes neuroblastoma cells to apoptosis." (PMID 39039334, 2024). "Treating human neurons (induced pluripotent stem cell [iPSC]-derived or neuroblastoma SH-SY5Y cells) for 24 h with etidronate, alendronate, or thonzonium resulted in dose-dependent decreases in ataxin-2 protein levels." (PMID 36288714, 2022). "Importantly, we followed up on hits of interest to confirm that their regulation of ataxin-2 was conserved in more disease-relevant neuronal cell lines, such as SH-SY5Y neuroblastoma cells, human iPSC-derived neurons, and mouse cortical neurons." (PMID 36288714, 2022). "We found that cytoplasmic CREST-GFP aggregates sequester endogenous ATXN2 in human neuroblastoma cells under these conditions, whereas in non-transfected (NT) cells and in cells lacking these aggregates, ATXN2 remains diffusely distributed (top and bottom)." (PMID 31390360, 2019). "We have observed that ELF2 acts as a repressor of ATXN2 gene expression in neuroblastoma cells and that mt-ELF2 will not be likely to regulate its expression." (PMID 29628936, 2018). "We further validated hits in the human neuroblastoma cell line SH-SY5Y, where many—but not all—had a significant effect on ataxin-2 protein levels." (PMID 36288714, 2022).
breast carcinoma (5 papers, 2015 to 2024). "Especially, the methylation at CpG sites cg07932199 (ATXN2) was suggested with nearly 100% posterior probability of sharing causal variants (rs7310615 and rs3184504) with the susceptibility to four cancers: breast cancer, CRC, endometrial cancer and lung cancer." (PMID 37449541, 2023). "Interestingly, the ATXN2 gene has been found to be altered by copy number, mutation or expression in ~9% of breast cancers in the TCGA dataset and this may be another mechanism for tumour cells to potentiate EGFR signalling." (PMID 25969993, 2015). "With the progress of research, ATXN2 has also been found to play an important role in the development of various cancers, including breast cancer, gastric cancer, pancreatic cancer, colon cancer, and esophageal cancer." (PMID 39039334, 2024). "The highly correlated variation in the SH2B3/ATXN2/ BRAP locus (including rs3184504) is related to the age of parental death, suggesting that ATXN2 may also play a regulatory role in breast cancer." (PMID 39039334, 2024). "Moreover, Park & al. demonstrated in MCF10 breast cancer cells overexpressing SRSF6 that ITGA5, ITGB2 and ITGB6 were overexpressed and alternative splicing variants of ITGB2, ITGB4, SRSF6 and ATXN2 were detected." (PMID 37904233, 2023).
coeliac disease (5 papers, 2014 to 2025). "Replicated associations that were genome-wide significant in their own right in FinnGen (class 1) included for instance that between rs10774625 (nearest gene: SH2B3/ATXN2) and coeliac disease (p = 1.3×10−6 in UK Biobank; p = 2.1×10−10 in FinnGen)." (PMID 40493586, 2025). "We replicate the association between rs3184504 (mapped to SH2B3/ATXN2), previously shown to be associated with celiac disease, in our extreme longevity phenotype, but not the other three variants (although they are associated with continuous parent's age at death p<0.05)." (PMID 27015805, 2016). "As regards coeliac disease diagnosis above 7 years of age in the case–control analysis, rs653178 (at SH2B3/ATXN2), rs13010713 (at ITGA4/UBE2E3), rs13151961 (at IL2/IL21), rs11712165 (at CD80) and rs10936599 (at MYNN) showed an association." (PMID 33446885, 2021).
dementia (5 papers, 2010 to 2022). Loss of intellectual abilities interfering with an individual's social and occupational functions. "Similarly, a girl aged 10 years with intellectual disability was found to have a 99-repeat expansion in ATXN2, despite the fact that both parents were designated as unaffected, and a girl aged 18 years with dementia was found to carry a 69-repeat expansion in ATN1." (PMID 35182509, 2022).
Cognitive impairment (4 papers, 2022 to 2025). Abnormal cognition is characterized by deficits in thinking, reasoning, or remembering. "ASOs targeting ATXN2 may provide effective interventions for sleep deprivation‐induced cognitive impairments." (PMID 37072935, 2023). "A novel finding in this paper is the identification of a correlation between ATXN2 polyQ intermediate number of repeats in ALS and cognitive impairment." (PMID 36008116, 2022).
dentatorubral-pallidoluysian atrophy (4 papers, 2016 to 2017). Dentatorubral pallidoluysian atrophy (DRPLA) is a rare subtype of type I autosomal dominant cerebellar ataxia (ADCA type I). "Using similar structure probing approaches, several “slipped” hairpin variants have been observed for CAG repeats of the atrophin (ATN1), ATXN2, and ATXN3 transcripts, which are implicated in dentatorubral-pallidoluysian atrophy (DRPLA), SCA2 and SCA3, respectively." (PMID 28442996, 2017).
hereditary ataxia (4 papers, 2013 to 2022). An instance of an atactic disorder that is caused by an inherited genomic modification in an individual. "The interaction between ELF2,ATXN2, and ELOVL5 genes found suggests that the regulation of expression in these genes could potentially be a shared mechanism in hereditary ataxias." (PMID 29628936, 2018). "In patients with suspected hereditary ataxia, we identified expansions in loci that had not been assessed as part of routine diagnostic workup within the NHS at the time of recruitment, including ATN1, ATXN2, ATXN3, ATXN7, CACNA1A, FXN, TBP, and HTT." (PMID 35182509, 2022).
tauopathies (4 papers, 2017 to 2020). "Similarly, a deficiency of Smpd3 encoding nSMase2, as detected in the KIN nervous tissue, was reported to cause TDP-43 neurotoxicity and tauopathy, while ataxin-2 depletion protects against TDP-43 aggregation and tauopathies." (PMID 31766565, 2019). "However, no follow up studies have clarified this association, and thus future work is required to determine if Ataxin-2 proteins in fact play a role in the development of tauopathies." (PMID 28587229, 2017).
Anxiety (3 papers, 2009 to 2025). Intense feelings of nervousness, tension, or panic often arise in response to interpersonal stresses. "Overexpression of pathogenic human ATXN2 in cerebellar Purkinje cells would be expected to lead to progressive degeneration of these neurons causing compromised locomotive behavior such as speed of swimming and turning behavior as well as an increase in anxiety (novel tank test, thigmotaxis)." (PMID 41462986, 2025). "In both tests, Atxn2 ko mice showed signs of reduced fear and anxiety with heterozygotes exhibiting an intermediate phenotype." (PMID 19617910, 2009). "During open cage testing, we observed that in one of our cohorts, Atxn2 ko animals spent more time in the center of the open cage, a potential indication of reduced anxiety." (PMID 19617910, 2009).
chronic kidney disease (3 papers, 2013 to 2023). Impairment of the renal function secondary to chronic kidney damage persisting for three or more months. "In addition, from our global proteomics analyses, we identified ATXN2 as a “top hit”; apart from one report regarding ATXN2 as a novel locus in chronic kidney disease, no other findings have been thus far reported with respect to kidney cancer." (PMID 37139155, 2023).
cognitive decline (3 papers, 2018 to 2025). "The homozygous case, ATX-05, with 27/27 CAG repeats in the ATXN2, consisted of patients that were 67 years old on average and presented with significant cognitive decline, reflected by a MoCA score of 8.5, and was also homozygous E3/E3 for APOE." (PMID 41009775, 2025).
esophageal squamous cell carcinoma (3 papers, 2022 to 2024). Esophageal squamous cell carcinoma (ESCC) is a type of esophageal carcinoma (EC) that can affect any part of the esophagus, but is usually located in the upper or middle third. "In esophageal squamous cell carcinoma (ESCC), ATXN2 has been found to be significantly elevated." (PMID 39039334, 2024). "These include ATXN2 (Ataxin-2), which mediates the translation of TNFR1, promoting esophageal squamous cell carcinoma, or ITGA4, a cytoskeleton protein involved in gastric cancer cells migration." (PMID 36833303, 2023). "For instance, ATXN2 has been shown to enhance the translation of TNFRSF1A by binding to m6A-modified TNFRSF1A mRNA, leading to the activation of NF-κB and MAPK pathways, thereby promoting esophageal squamous cell carcinoma (ESCC) tumorigenesis and progression." (PMID 39039334, 2024).
gastric cancer (3 papers, 2022 to 2024). A primary or metastatic malignant neoplasm involving the stomach. "Upregulated ATXN2 expression also leads to increased PD-L1 expression, impacting gastric cancer immunotherapy." (PMID 39039334, 2024). "In gastric cancer, SP1 transcriptionally regulates ATXN2 expression, activating the PI3K/AKT signaling pathway, which contributes to ATXN2's anti-apoptotic and chemoresistant properties in gastric cancer." (PMID 39039334, 2024).
hypothyroidism (3 papers, 2018 to 2023). Abnormally low levels of thyroid hormone. "Some of the hypothyroidism loci had already previously been implicated in hypothyroidism through GWAS, including TPO, FOXE1, VAV3, and a variant in ATXN2 (rs597808) in high linkage disequilibrium (LD) with the R262W polymorphism in SH2B318." (PMID 30367059, 2018).
motor neuron degeneration (3 papers, 2015 to 2019). "It remains unclear whether the changes of ribosomal translation and protein synthesis in ATXN2-ablated tissue underlie the previously reported neuroprotective effect of ATXN2 deficiency for motor neuron degeneration." (PMID 25721894, 2015). "The underlying protein, which is mutated in SCA2 and also acts as risk factor in the motor neuron degeneration of Amyotrophic Lateral Sclerosis (ALS), has been identified and named ataxin-2 (gene symbol ATXN2)." (PMID 33324888, 2019). "It is interesting to ask by what mechanisms the converse depletion of ataxin-2 can be neuroprotective both in SCA2 mouse models and in mouse models of motor neuron degeneration with an ALS phenotype by TDP-43 neurotoxicity." (PMID 31766565, 2019).
pancreatic adenocarcinoma (3 papers, 2022 to 2024). "ATXN2 has been reported to be overexpressed in pancreatic adenocarcinoma (PAAD) tumor tissues, and overexpression of ATXN2 promotes PADD cell proliferation, migration, and invasion." (PMID 35281269, 2022). "In pancreatic adenocarcinoma (PAAD), ATXN2 is upregulated in PAAD tissues and exhibits negative associations with miR-873-3p levels but positive associations with LINC00941 levels." (PMID 39039334, 2024).
pancreatic cancer (3 papers, 2015 to 2024). "For example, one of our hits mapped to the Ataxin two (Atxn2) gene, expression of which has been linked to pancreatic cancer development in smokers." (PMID 38436597, 2024).
retinal degeneration (3 papers, 2019 to 2024). Degeneration of the retina. "In contrast, expression of the 6× ATXN2-CAA/G65 and 6× ATXN2-CAA64 transgenes caused little to no retinal degeneration." (PMID 34077532, 2021).
Tremor (3 papers, 2024 to 2025). An unintentional, oscillating to-and-fro muscle movement about a joint axis. "With respect to parkinsonian symptoms, there was a significant increase in rigidity (p = 0.0402) and a tendency toward a non-significant increase in resting tremor (p = 0.2230) when the ataxic SCA3 MC with ATXN2 27-30Q were compared with that without intermediate ATXN2 repeats." (PMID 40684213, 2025).
type 2 diabetes (3 papers, 2013 to 2025). "Additionally, metabolic traits such as type 1 and type 2 diabetes were linked to ATXN2 and ATXN7, which is in line with the fact that metabolic dysfunction is observed in several polyQ disorders." (PMID 41254939, 2025).
Abdominal obesity (2 papers, 2011 to 2025). Excessive fat around the stomach and abdomen. "Complete depletion of ATXN2 in knockout mice showed slight deficits in motor performance, reduced fertility, locomotor hyperactivity, abdominal obesity and hepatic steatosis in older animals, as well as effects on the circadian system." (PMID 41462986, 2025).
asthma (2 papers, 2022 to 2025). "The meta-analysis revealed that ABO and ATXN2 contain variants with pleiotropic effects on both COVID-19 and asthma." (PMID 35386719, 2022). "Since ATXN2 has been associated with asthma at the genome-wide level, our meta-analysis suggests ATXN2 may be a novel risk gene for COVID-19." (PMID 35386719, 2022). "Our meta-analysis supports that the effects of variation within the ABO and ATXN2 genes are shared between COVID-19 and asthma." (PMID 35386719, 2022).
autosomal dominant cerebellar ataxia (2 papers, 2017 to 2022). A clinically and genetically heterogeneous group of neurodegenerative diseases characterized by a slowly progressive ataxia of gait, stance and limbs, dysarthria and/or oculomotor disorder, due to cerebellar degeneration in the absence of coexisting diseases. "Spinocerebellar ataxia type 2 (SCA2) is an autosomal dominant cerebellar ataxia that occurs as a consequence of abnormal CAG expansions in the ATXN2 gene." (PMID 28955296, 2017).
Cerebellar atrophy (2 papers, 2023 to 2025). Cerebellar atrophy is defined as a cerebellum with initially normal structures, in a posterior fossa with normal size, which displays enlarged fissures (interfolial spaces) in comparison to the foliae secondary to loss of tissue. "After a clinical evaluation that evidenced ataxic signs, a brain MRI was performed, showing cerebellar atrophy, and genetic testing confirmed the presence of a pathologic 61 CAG ATXN2 allele." (PMID 40002489, 2025).
COVID-19 (2 papers, 2022 to 2024). A disease caused by infection with severe acute respiratory syndrome coronavirus 2. "Furthermore, ATXN2 has emerged as a potential risk gene for the novel coronavirus (COVID-19), and its effects are shared with asthma at the genome-wide level." (PMID 39039334, 2024).
developmental delay (2 papers, 2009 to 2020). "It is likely that ATXN2 aberration causes a brain developmental issue as reflected in the developmental delay in patient# 9 as well." (PMID 32999401, 2020).